HIF1A (hypoxia inducible factor 1 subunit alpha)
Diseases named in the same sentence as HIF1A in open-access papers (continued):
Sharing a sentence is not in itself a finding about the gene and the disease.
tumor (continued). "Effects were also demonstrated through in vivo experiments, 25 being able to suppress tumor growth of 4T1 cells in BALB/c mice by inhibiting the accumulation of HIF-1α in tumor tissue." (PMID 38667760, 2024). "Studies also suggest that hypoxic environments enhance tumor angiogenesis by overexpressing eIF5A2, which activates the HIF‐1α‐mediated signaling pathway, thus promoting tumor growth and dispersal." (PMID 39415846, 2024). "This aspect is particularly relevant to our research focus on elucidating the role of HIF-1α in tumor progression and response to therapy, as the tumor microenvironment significantly influences HIF-1α activity and downstream signaling pathways." (PMID 38962320, 2024). "In GBM cells, AKT signaling stabilizes HIF-1α, while the deregulation of AKT activity through loss of the tumor suppressor protein PTEN during malignant progression contributes to tumor expansion." (PMID 39055895, 2024). "Within the hypoxic tumor microenvironment typical of PDAC, HIF-1α promotes metabolic reprogramming, favoring glycolysis and angiogenesis, thereby supporting tumor growth and survival." (PMID 39682281, 2024). "In the tumour edge regions of the control animals, the hypoxia marker HIF1α was detected in the nucleus and cytoplasm; on the other hand, in the treated animals, HIF1α was preferentially located in the cell nucleus." (PMID 39061796, 2024). "The complex relationship between HIF-1α expression and various factors, including the mutational landscape of HCC, the tumour microenvironment, and the administration of other therapeutic agents, requires comprehensive consideration." (PMID 38993573, 2024). "Hypoxia-inducible factor 1 alpha (HIF-1α) stands as a pivotal transcription factor in cancer progression and targeted therapies, closely linked to tumor metastasis, angiogenesis, poor patient prognosis, and resistance to cancer treatments." (PMID 39108268, 2024). "Subsequently, we performed survival analysis using the Kaplan–Meier method to explore the impact of EGLN and HIF1A mRNA levels in tumor tissues on patients’ overall survival." (PMID 38928200, 2024). "These compounds can interfere with HIF-1α's activity, stability, or interaction with other proteins, thereby inhibiting tumor growth and metastasis." (PMID 39493156, 2024). "SMURF2’s role as both a tumor suppressor and an oncogene highlight its complexity and potential as a context-dependent target, while its regulation of HIF1α provides new insights into controlling hypoxia-driven cancer progression." (PMID 39697237, 2024). "In this study, we reported that radiotherapy ameliorated tumor hypoxia, downregulated HIF-1α expression and MIF secretion in NSCLC, and inhibited the binding of MIF to CD74 in microglia." (PMID 38685050, 2024). "The clear cell phenotype has been attributed to the activation of HIF1a resulting in a status of pseudohypoxia and, consequently, in lipid and glycogen accumulation within the tumor cells." (PMID 38619811, 2024). "The hypoxic tumor microenvironment leads to HIF-1 activation via the assembly of the HIF-1α and HIF-1β subunits." (PMID 38904007, 2024). "Its utilization can effectively disrupt the activity of HIF-1α and enhance the body’s tumor-suppressing capability." (PMID 38794281, 2024). "h-LEH combined with chemotherapeutic drugs by inhibiting HIF-1α activity, which prevented angiogenesis and inhibited tumor growth and metastasis." (PMID 38880905, 2024). "HIF-1α, a hypoxia-inducible factor, is often upregulated to exhibit adaptive responses to the hypoxic condition of tumor cells." (PMID 39339168, 2024). "The hypoxic region inside the tumor tissue was targeted by the anti-Hif1a Ab developed from the AF488-labeled 2nd Ab." (PMID 38481819, 2024). "HIF-1a is in an interplay with all hallmarks of cancer, like genomic instability, inflammation, vascularization, tumor invasion and survival, amongst others." (PMID 38257813, 2024).
tumor (continued). "When stimulated by glycolysis and fibronectin 1 (FN-1), HLA-DR- and CD86-high macrophages exhibit a glycolytic phenotype, impeding the secretion of the anti-tumor agent IL-12 p70 through the PKM2/HIF-1α axis." (PMID 38891772, 2024). "Recent research indicates that specific HIF-1α subtypes are present in several solid tumors, potentially contributing to tumor progression." (PMID 38799423, 2024). "HIF-1α supports the formation of new blood vessels, enhancing the tumor’s ability to thrive in low-oxygen environments, contributing to aggressive tumor growth." (PMID 39063221, 2024). "Oxidative stress promotes the production of angiogenic factors, such as vascular endothelial growth factor (VEGF) and hypoxia-inducible factor 1-alpha (HIF-1α), which stimulate the formation of new blood vessels to support tumour growth and metastasis." (PMID 39204080, 2024). "Tumor-derived lactate activates HIF-1α to promote TAMs glycolysis, M2 polarization, and tumor-promoting functions." (PMID 38840205, 2024). "Hypoxia inducible factor‐1α (HIF‐1α) was favorably correlated with the depth of tumor invasion, lymph node metastasis and advancing tumor stage." (PMID 38349050, 2024). "Hypoxia-inducible factor 1-alpha (HIF1A) is a key transcription factor aiding tumor cells’ adaptation to hypoxia, regulated by the prolyl hydroxylase family (EGLN1-3) by directing toward degradation pathways." (PMID 38928200, 2024). "SMURF2, an E3 ubiquitin ligase, plays a crucial role in HIF1α degradation, limiting HIF1α’s ability to promote tumor adaptation to hypoxic environments." (PMID 39697237, 2024). "In vivo, borneol treatment was found to enhance the anticancer effect of TMZ and delay tumor progression, and this effect was closely related to its ability to promote the autophagic degradation of HIF-1α." (PMID 38188151, 2024). "Cancer therapy: HIF-1α levels, if reduced, have been seen to decrease tumor growth and metastasis by a large percentage." (PMID 39493156, 2024). "We confirmed that hypoxia induces high expression of highly active aerobic glycolysis via upregulation of HIF-1α, promoting tumor progression by providing energy and macromolecular substances." (PMID 38577616, 2024). "Blocking the binding of HDAC2 to the promoter of HIF-1α can activate the transcription of HIF-1α, which can promote tumor growth and metastasis." (PMID 39876842, 2024). "Propofol can downregulate HIF-1α in tumor cells and inhibit tumor angiogenesis and tumor growth in mice." (PMID 39525113, 2024). "This is due to its role in regulating HIF1α (Hypoxia-inducible factor 1-alpha), as well as other proteins involved in tumor suppression." (PMID 37883464, 2024). "These inhibitors intend target the inhibition of HIF-1α, which is important for tumor growth and proliferation." (PMID 39493156, 2024). "Repression of HIF-1α expression: Small interfering RNAs (siRNAs) or antisense oligonucleotides can be utilized to specifically block HIF-1α expression, leading to reduced levels and impeded tumor growth." (PMID 39099978, 2024). "Previous research has shown that resveratrol can counteract hypoxia-induced tumor aggression in SAOS-2 cells by downregulating HIF-1α." (PMID 39852136, 2024). "In conclusion, HIF1α is a central regulator of tumor adaptation to hypoxic conditions through its influence on angiogenesis and metabolic reprogramming, which support tumor growth and survival." (PMID 39697237, 2024). "In the context of cancer, HIF-1α is often upregulated in tumor cells due to the hypoxic microenvironment commonly found in solid tumors." (PMID 38474118, 2024). "CA9 is considered a marker of hypoxia and is activated when hypoxia-inducible factor 1-alpha (HIF-1α) accumulates, and hypoxia has been reported to be associated with increased tumor cell viability and malignancy and to promote tumor cell growth." (PMID 39471162, 2024).
tumor (continued). "In contrast, deletion of HIF-1α in TCRP1A CD8 T cells showed attenuated anti-tumor activity, confirming the pivotal role of HIF-1α signaling in the modulation of CD8 T-cell responses against tumors." (PMID 39242595, 2024). "In tumor vascular endothelial cells (ECs), under hypoxic conditions, HIF-1α activates the transcription of diacylglycerol kinase gamma (DGKG)." (PMID 39223632, 2024). "Manipulation of TGFβ, PGE2 or the transcription program controlled by HIF-1α, was insufficient to drive the full array of changes that define tumor-retained NK cells, implying that the coordinated action of multiple signals orchestrates this fate." (PMID 38267402, 2024). "This is also supported by HIF1a-mediated lactate-induced arginase expression in macrophages, leading to tumor progression by cell proliferation." (PMID 39104525, 2024). "mTOR signaling pathway can normally activate GLUT1, a key glycolysis protein, which can enhance the Warburg effect of tumor cells through the transcription factors HIF1α and MYC." (PMID 39003253, 2024). "Low oxygen levels, along with the influence of hypoxia-inducible factor 1 alpha (HIF1α) and oxidative stress pathways, contribute to mitochondrial dysfunction and morphological alterations in tumor-infiltrating NK cells." (PMID 39763648, 2024). "Together, our results suggest a profound antitumor effect of JHU083 via impaired tumor cell metabolism, leading to disruption of HIF-1α and c-MYC signaling." (PMID 38701369, 2024). "Through the activation of PI3K, MAPK, NF-kB and other signaling pathways that promote tumor development, HIF-1α responds to growth factor and cytokine stimulation and promotes the survival of cancer cells in hypoxic environments." (PMID 38364250, 2024). "Severe hypoxic tumor cores with cells expressing HIF-1α are localized to the nuclei in the larger tumors, whereas weaker and more diffused HIF-1α signals are present throughout the smaller tumors." (PMID 38544822, 2024). "The VHL protein is known as a tumor suppressor and E3 ligase that ubiquitinates HIF1α for degradation." (PMID 38491188, 2024). "Numerous studies have demonstrated that HIF-1α regulates these processes as a central player in tumor progression." (PMID 39858431, 2024). "Triple combination therapy involving HIF-1α siRNA, OXA, and IMQ significantly retarded tumor growth and led to elevated levels of cytokines linked to cellular immunity (INF-γ and IL-12) compared with those in the other groups (P < 0.05)." (PMID 39614894, 2024). "In the hypoxic TME, HIF-1α promotes neutrophil survival by enhancing glycolysis, while HIF-2α supports the survival of tumor-associated neutrophils (TANs)." (PMID 39119332, 2024). "confirms that in BC‐associated macrophages, long noncoding RNAs are regulated by the transcription factor HIF‐1α, playing a vital role in the glycolysis and drug resistance of tumour cells." (PMID 39107958, 2024). "In NSCLC, HIF-1α is overexpressed, driving glycolysis even in the presence of oxygen (the Warburg effect) and facilitating tumor adaptation to hypoxia." (PMID 39682234, 2024). "Previous studies have reported activation of lncRNAs STEAP3-AS1 and LUCAT1 by HIF-1α leads to promoted tumor progression." (PMID 38740637, 2024). "2ME2 depolymerizes microtubules in tumor cells by interacting with colchicine binding site on β-tubulin, leading to the protein-level inhibition of HIF-1α downstream." (PMID 38416732, 2024). "Elevation of O2 levels at tumor sites downregulates HIF-1α, affecting the metabolism of tumor cells and Treg cells, and ultimately reducing cancer cell proliferation." (PMID 39575238, 2024). "While we have previously reported a growth-suppressive effect of C/EBPδ under normoxic conditions in vitro, we here show that in hypoxia and in vivo, these tumor suppressor effects are abrogated, presumably due to reciprocal activation of C/EBPδ and HIF-1α." (PMID 39273396, 2024).
tumor (continued). "miR-142: It is reported that miR-142 restored levels are closely related to the limitation of the tumor invasive behavior and growth via regulating the expression of hypoxia-inducible factor 1-alpha (HIF-1a), which is a transcription factor." (PMID 38542378, 2024). "Research has shown that ZFP36 regulates tumorigenesis by destabilizing the expression of critical genes implicated in both, tumor onset and tumor progression, such as HK2, HIF1α, and c-Myc." (PMID 39026155, 2024). "While excessive ROS can induce ferroptosis in tumor cells, playing a role in cancer suppression, ROS can also promote tumor progression and metastasis by stabilizing HIF1α." (PMID 38978503, 2024). "Significant positive correlations with GPX4 (ferroptosis), ACSL4 (fatty acid metabolism), SOD2 (antioxidant), HIF1A (tumor growth and metastasis), FAT1 (fatty acid metabolism) and IREB2 (Iron-responsive element)." (PMID 38206305, 2024). "Delivering ZA to tumor tissues via nanoparticles reduces Ras/ERK1/2/HIF-1a axis activity and P-glycoprotein expression and, as a result, increases the number of DCs and reduces the number of infiltrating Tregs." (PMID 39434182, 2024). "Recently, several research groups have directed their efforts toward stabilizing HIF-1α, specifically in lymphocytes, to enhance tumor control." (PMID 39242595, 2024). "Following intraperitoneal injection of the tumor cells, we confirmed the expression of hypoxia-inducible factor-1α (HIF-1α) that remained stable after irradiation." (PMID 38339228, 2024). "The inhibitors targeting HIF-1α also can inactivate the tumour microenvironment-derived extrinsic signals (CSF1 and CCL5) to further improve the response of targeting intrinsic molecular pathways to overcome the resistance to anti-VEGF therapy." (PMID 39267775, 2024). "It not only adversely impacts the treatment efficacy of PDT25,26, but also dramatically activates the expression of hypoxia-inducible factor 1α (HIF-1α) that regulates multiple pivotal steps of tumor metastasis." (PMID 38280861, 2024). "This crucial role is further supported by clinical findings in colorectal cancer, where HIF-1α positively correlates with VEGF and is associated with an advanced tumor stage and metastasis." (PMID 38542288, 2024). "HIF-1α is a transcription factor that plays a central role in the response to low oxygen levels, or hypoxia, within the tumor microenvironment." (PMID 38257813, 2024). "The association between HIF-1α expression in ICs and higher histologic grades highlights the importance of HIF-1α within the tumor microenvironment." (PMID 39202223, 2024). "We then transferred HIF-1α KO or PHD2/3 KO CD8 T cells intravenously in tumor-bearing TiRP mice, which were shown to be completely resistant to ACT with activated TCRP1A CD8 T cells." (PMID 39242595, 2024). "LY6E’s interaction with the PI3K/Akt pathway, and its subsequent influence on HIF-1α transcription, outlines a mechanism pivotal to pathological processes such as tumor growth and angiogenesis." (PMID 38674087, 2024). "Both in vivo and in vitro experiments confirmed that combining ACF with chemotherapy achieved remarkable tumor inhibition by enhancing ROS production and suppressing HIF-1α expression." (PMID 38794281, 2024). "Expression analysis based on TCGA data revealed differential expression patterns of prolyl hydroxylases and HIF1A that varied across tumor types." (PMID 38928200, 2024). "PX-478 has shown antitumor activity against various tumor xenografts by inhibiting HIF1α and its target genes, such as VEGF and GLUT1, inducing glycolysis inhibition." (PMID 38786726, 2024). "Target genes regulated by HIF-1α play important roles in various aspects of tumor cell energy metabolism, apoptosis, angiogenesis, proliferation, and metastasis." (PMID 39619441, 2024).
tumor (continued). "This molecule can promote EMT to participate in tumor cell migration and invasion by upregulating MMP2, MMP9 and other factors and can directly activate VEGF and HIF-1α to promote tumor angiogenesis and other aspects to promote tumor metastasis." (PMID 38486162, 2024). "As tumor growth surpasses the capacity of blood vessel supply, hypoxia intensifies, prompting cancer cells to upregulate HIF-1α." (PMID 39091919, 2024). "Our previous study revealed that HIF1α collaborates with SP1 to regulate the cyclization of circ_0001875 in a hypoxic tumor microenvironment." (PMID 39030638, 2024). "For example, HIF-1α was found to promote the expression of sialyl-Tn (STn), MMP1, and UCA1, causing a weakened intercellular adhesion and thus promoting tumor metastasis." (PMID 37475553, 2024). "In normoxic and hypoxic environments, HIF-1α exhibits distinct pathological mechanisms and actively participates in molecular mechanism regulation of tumor cells through corresponding signaling pathways." (PMID 38327979, 2024). "Reduction of HIF-1α effectively stimulates the conversion of M2-type macrophages to M1-type, and release of DAMPs enhance the anti-tumor immune response." (PMID 38853203, 2024). "BAY87-2243 is a selective HIF-1α inhibitor that can effectively inhibit HIF-1α protein levels in tumor cells." (PMID 37588219, 2024). "Hypoxia has been found to enhance lactate production and tumor growth through activation of HIF1-α, GLUT1, HK2, PKM2, PDK, ENO1 or LDHA." (PMID 38233839, 2024). "Our results highlighted the efficacy of anti-HIF-1α siRNA2-loaded NPs for gene knockdown both in vitro and in vivo, proving their potential in tumor targeting and for their use in combination therapy with anti-tumoral drugs and/or radiotherapy." (PMID 39458615, 2024). "Densitometric examination of the expression of the protein HIF1α in six tumor samples and the corresponding four adjacent tissues." (PMID 39132498, 2024). "Inhibiting HIF-1α promoted NK cell activity and inhibited tumor progression in humans and mice, underscoring the crucial role of HIF-1α in maintaining tumor immunosurveillance in human NK cells beyond its function as a hypoxia-responsive transcription factor." (PMID 38892084, 2024). "These RNA-mimicking methodologies can effectively intervene with the spurt of HIF-1α in the process of tumor development." (PMID 39493156, 2024). "HIF-1α expressions in the tumor tissues decreased significantly in the PCa+LDH-A inhibitor + Docetaxel treatment group compared to the PCa group (p < 0.01)." (PMID 38213726, 2024). "In hypoxic environments, HIF-1α upregulates anti-apoptotic genes and activates PD-L1 in tumor cells, enabling immune evasion and enhancing invasion and migration." (PMID 39737184, 2024). "PFKP, targeted by hypoxia-inducible factor 1 alpha (HIF1a), has close relation with tumor aerobic glycolysis, tumor growth, immune evasion and reducing metabolic load under glucose starvation." (PMID 38977778, 2024). "Sorafenib: Sorafenib is a small molecule that has multiple kinase profiles to inhibit tumor cell proliferation and has features of HIF-1α suppression." (PMID 39493156, 2024). "When tumour cells acquire the ability to metastasise one of the best-studied metastasis drivers is HIF1A." (PMID 38902533, 2024). "This pioneering work highlights the potential of targeting CDKs with specific inhibitors like palbociclib to destabilize HIF1α, offering fresh avenues to impede the hypoxic response integral to tumor survival and proliferation." (PMID 39697237, 2024).